TNF (tumor necrosis factor)
Diseases named in the same sentence as TNF in open-access papers (continued):
Sharing a sentence is not in itself a finding about the gene and the disease.
rheumatoid arthritis (continued). "Immunosuppressants such as HIV infection or anti-tumor necrosis factor (TNF) treatment for rheumatoid arthritis may lead to the reactivation of these bacteria." (PMID 22003408, 2011). "Especially in pre-existing osteoarthritis and in rheumatoid arthritis with abundant expression of TNF-α and IL-1β the use of FTY720 may accelerate cartilage degradation." (PMID 22151889, 2011). "Observational data on patients treated with anti-TNF therapies for moderate to severe rheumatoid arthritis, ankylosing spondylitis, psoriatic arthritis and other rheumatologic indications are available from the British Society of Rheumatology Biologics Register (BSRBR,)." (PMID 21672203, 2011). "Interestingly, anti-TNF-α treatment in patients with rheumatoid arthritis results in decreased plasma BDNF." (PMID 21958434, 2011). "Moreover, a TNF-alpha antagonist therapy in rheumatoid arthritis patients led to enhanced PON1 levels concurrent with elevated anti-oxidative capacities of HDLs and lowered inflammatory status." (PMID 21569287, 2011). "Both the cell-associated and the secreted forms of TNF-α are biologically active in the form of homotrimers and inhibition of TNF-α has proven to be an effective therapy for a number of inflammatory diseases (e.g. rheumatoid arthritis)." (PMID 21991353, 2011). "However, treatment of rheumatoid arthritis and Crohn's disease with anti-TNF drugs, and especially the monoclonal antibodies, was shown to be associated with an increased risk of reactivation of tuberculosis." (PMID 22162712, 2011). "Thus, similarly to adults with rheumatoid arthritis, the proinflammatory cytokines (TNF-α, IL-1) produced by synovial membrane are responsible for excessive bone resorption also in adult patients with JIA." (PMID 21403891, 2011). "TNF antagonists are an effective treatment for rheumatoid arthritis." (PMID 21492465, 2011). "We believe that this approach has significant potential given the overall favorable safety profile associated with non-CNS penetrant TNF-α inhibitors (including sTNFR-Fc) for treatment of rheumatoid arthritis and other conditions." (PMID 21569583, 2011). "Also, our patients come from a primary care setting, and even if 60% of the patients had hand OA, their baseline measure in GAT was better than in patients with rheumatoid arthritis, after one year of anti-TNF therapy." (PMID 20969809, 2010). "Earlier data obtained from the rheumatoid arthritis patients treated with TNF-α antagonists showed that blocking TNF-α could lead to reactivation of tuberculosis." (PMID 20537163, 2010). "Also, the chronic inflammatory condition rheumatoid arthritis, which shares many characteristics with periodontitis, has been successfully treated using TNFα blockers, further highlighting TNFα as a key inflammatory mediator in chronic inflammatory conditions." (PMID 20398340, 2010). "As such, Themis2 could represent a novel site at which therapies designed to intervene in chronic inflammatory diseases involving TNF, such as rheumatoid arthritis, might usefully be targeted." (PMID 20644716, 2010). "Moreover, as patients with rheumatoid arthritis have a higher rate of cancers than the general population, the connection between cancer and use of anti- TNF-alpha agents is unclear." (PMID 27713252, 2010). "For example, the anti-TNF-α antibodies infliximab, adalimumab, golimumab and certolizumab are commonly used in clinical practice for the treatment of patients with rheumatoid arthritis." (PMID 21179199, 2010). "While Th1 cytokines IFN-γ and TNF-α are critical for immune protection against tuberculosis in mice, the role of human TNFα anti-tuber culosis immunity is demonstrated in the subjects who receive anti-TNF mAb treatment of rheumatoid arthritis, and develop reactivation tuberculosis." (PMID 19730727, 2009).
rheumatoid arthritis (continued). "Suppression of TNF-α production by some plant extracts, such as Dioscoreae Rhizoma, Prunella vulgaris, and Salvia miltiorrhiza bunge is suggested to ameliorate several inflammatory disorders, including rheumatoid arthritis, endotoxemia, and anaphylaxis." (PMID 19594948, 2009). "Also, high levels of TNF-α present in synovial fluid from the TMJ are related to increased TMJ pain experience in rheumatoid arthritis patients." (PMID 19200377, 2009). "Additionally, in rheumatoid arthritis (RA) TMJ pain and tissue destruction are associated with elevated synovial levels of TNF-α." (PMID 19200378, 2009). "Anti-TNF therapy is frequently used in patients with rheumatoid arthritis, and may promote regeneration of eroded joints." (PMID 19916697, 2009). "Treatment with TNF antagonists has improved the outcome of rheumatoid arthritis (RA) patients." (PMID 19627609, 2009). "Production of TNF-α, IL-6, IL-8, histamine and other inflammatory mediators by the activated mast cells could drive synovitis in RA, and it has been shown that mice deficient in mast cell activation were resistant to the induction of arthritis in the K/BXN model of rheumatoid arthritis." (PMID 19133134, 2009). "Anti-TNF therapy used in treatment of rheumatoid arthritis produces profound analgesia, indicating that TNF-α and its receptors may be good therapeutic targets in other chronic inflammatory pain conditions." (PMID 19531269, 2009). "TNFα is increased in the synovial fluid of patients with rheumatoid arthritis and osteoarthritis." (PMID 19144181, 2009). "There is conflicting information about the safety TNF-alpha blocking agents, which have been primarily used in the treatment of rheumatoid arthritis, with serious infections, cardiovascular disease and malignancies being the most frequent serious adverse events." (PMID 20016776, 2009). "The British Society for Rheumatology Biologics Register reported that, among 8672 patients with rheumatoid arthritis treated with anti-TNF therapy, there were 23 reports of a new onset of psoriasis in patients with no previous history of psoriasis and one patient with a family history of psoriasis." (PMID 18727822, 2008). "Although less successful than anti-TNF therapies in rheumatoid arthritis (RA), there appears to be considerable benefit in the management of Juvenile arthritis (Still's disease), and it is the treatment of choice in the rare autoinflammatory illnesses typified by Muckle-Wells syndrome." (PMID 18298837, 2008). "Discontinuing TNF inhibitor therapy at 12 weeks may be premature in some rheumatoid arthritis patients." (PMID 18535115, 2008). "TNFα and IL-1β have been identified as key cytokines that are able to initiate inflammatory cascades during exacerbations of chronic inflammatory conditions such as rheumatoid arthritis, inflammatory bowel disease, and severe asthma." (PMID 18510721, 2008). "Rituximab is a chimeric mouse-human mAb that is specific for CD20 and is currently approved for the treatment of patients with non-Hodgkin's B-cell lymphoma and patients with rheumatoid arthritis who have exhibited an inadequate response to at least one TNF antagonist." (PMID 18786258, 2008). "While osteodestructive lesions in rheumatoid arthritis can already be inhibited by anti-TNF-α therapy after 1 year, inhibition of the osteoproliferation in patients with AS may need longer treatment." (PMID 18761747, 2008). "It enhances T cell activation, proliferation and secretion of pro-inflammatory cytokines such as TNFα and IL-21R has been shown to be over-expressed in inflamed synovial membrane and peripheral blood or synovial fluid leukocytes of rheumatoid arthritis patients." (PMID 18234077, 2008). "The data suggest that sparing membrane expressed TNF in therapeutic interventions neutralizing TNF such as in rheumatoid arthritis might reduce infectious complications." (PMID 18544042, 2008).
rheumatoid arthritis (continued). "Our data also suggest a possible mechanism contributing to rheumatoid arthritis pathogenesis, whereby miR-146a expression is increased but unable to properly function, leading to prolonged tumor necrosis factor-α production in patients with rheumatoid arthritis." (PMID 18759964, 2008). "About 30% of rheumatoid arthritis patients fail to respond adequately to TNFα-blocking therapy." (PMID 18454843, 2008). "The objective of this study was to assess whether clinical measures of rheumatoid arthritis activity and severity were influenced by tumor necrosis factor-alpha (TNF-α) promoter genotype/haplotype markers." (PMID 17408492, 2007). "It is possible to inhibit TNF-a, reducing its effects and prevent bone loss in illnesses such as rheumatoid arthritis, and there has been no specific investigation regarding cholesteatomas." (PMID 17505610, 2007). "Anti-TNF-α antibodies can also reduce and postpone bone destruction in rheumatoid arthritis." (PMID 17505610, 2007). "We and others have reported that rheumatoid arthritis (RA) synovial T cells can activate human monocytes/macrophages in a contact-dependent manner to induce the expression of inflammatory cytokines, including tumour necrosis factor alpha (TNFα)." (PMID 17101049, 2006). "Interestingly, phenelzine and other monoamine oxidase inhibitors have also been noted to induce remission of rheumatoid arthritis, a disease in which – as in Crohn's disease – TNFα has a central role." (PMID 16984660, 2006). "When FOXP3 expression was measured, a significant increase was found both in the combination and full dose anti-TNFα groups, underscoring likely effects of both therapeutic regimens on some Treg functions, in accordance with recent findings in Rheumatoid Arthritis patients." (PMID 17183718, 2006). "Lastly, future studies involving 12 weeks or long term anti-TNFα therapy may be useful against COPD (as observed in rheumatoid arthritis patients) and effectively combat pulmonary pathological consequences." (PMID 17034639, 2006). "Since TNF-α and IL-1β are implicated in arthritis, synovial concentrations of CXCL8 and CXCL10 were compared in patients suffering from crystal arthritis, ankylosing spondylitis, psoriatic arthritis and rheumatoid arthritis." (PMID 16846531, 2006). "In addition, the possible effect of biological therapy with anti-tumor necrosis factor (TNF)-α agents in rheumatoid arthritis patients on the levels and function of TREG cells has been recently explored by our and another group." (PMID 16677395, 2006). "This phenomenon might be important in the pathogenesis of conditions such as rheumatoid arthritis in which the synthesis of TNF is enhanced." (PMID 16684368, 2006). "Our objective was to clarify the heterogeneity in response to infliximab treatment in rheumatoid arthritis (RA); to this end, a bioassay was designed to explore the contribution of circulating tumour necrosis factor (TNF)-α bioactivity and its possible link to response." (PMID 15642135, 2005). "Tumour necrosis factor (TNF)-α plays a key role in the pathogenesis of rheumatoid arthritis (RA)." (PMID 16207322, 2005). "Subgroup analysis revealed that in rheumatoid arthritis (RA) patients, the probiotics group showed greater improvements in IL-6, IL-1β, and TNFα compared to the controls." (PMID 41978157, 2026). "Background/Objectives: Launched in Japan in 2022, ozoralizumab (OZR) is a novel, anti-tumour necrosis factor (TNF)-α inhibitor for treating rheumatoid arthritis (RA) that is refractory to conventional therapies." (PMID 41753109, 2026). "In osteoarthritis (OA) and rheumatoid arthritis (RA), the proinflammatory phenotype of the synovial macrophages (M1) is directly related to increased acetylation levels of the tumor necrosis factor α (TNF-α) and interleukin 1β (IL-1β) promoter regions." (PMID 41522338, 2026).
rheumatoid arthritis (continued). "In rheumatoid arthritis (RA), for example, elevated TNF-α drives immune-cell recruitment and stimulates the production of other inflammatory mediators, including matrix metalloproteinases, which lead to cartilage and bone destruction." (PMID 41596763, 2026). "The findings of this study demonstrate that dendritic cells (DCs) from patients with rheumatoid arthritis (RA) exhibit not only an altered surface phenotype but also heightened responsiveness to tumor necrosis factor alpha (TNF) stimulation." (PMID 40649852, 2025). "TNF abundance in the synovial fluid and tissues of patients with rheumatoid arthritis (RA) can induce pyroptosis, which is vital in sustained synovial inflammation by inducing nuclear factor (NF)-κB activation." (PMID 40704967, 2025). "However, systemic inhibition of TNF production can lead to undesirable side effects due to the weakening of the body’s defenses against pathogens; for example, there are cases of TB reactivation in patients with rheumatoid arthritis treated with TNF blockers." (PMID 40427602, 2025). "Similarly, KEGG enrichment analysis revealed that the main pathways in which the DEGs were involved included the rheumatoid arthritis, NF-kappa B, TNF, IL-17 and chemokine signalling pathways, as well as many other biological processes associated with cellular inflammatory responses." (PMID 40999451, 2025). "Moreover, STEAP4 exerted an inhibitory effect on TNF-α-induced rheumatoid arthritis." (PMID 41422349, 2025). "miR-451a was previously reported to be implicated in inflammatory pathways via upregulating in rheumatoid arthritis and systemic lupus erythematosus (SLE) and downregulating in influenza-infected dendritic cells which led to the increased secretion of inflammatory cytokines, e.g., IL6 and TNFα." (PMID 39934489, 2025). "However, recent meta-analysis indicates that anti-TNF-α therapy does not significantly increase lymphoma risk in patients with rheumatoid arthritis (RR = 1.43; 95% CI: 0.59–3.47)." (PMID 40711067, 2025). "TNF-α is a proinflammatory cytokine that is critical not only to the pathogenesis of MPN but also to that of rheumatoid arthritis (RA) and inflammatory bowel disease (IBD)." (PMID 40493419, 2025). "Moreover, after chronic administration in patients with rheumatoid arthritis, TNFα antibodies increase infections and reactivate latent tuberculosis, in addition to causing serious allergic reactions, lymphomas, congestive heart failure and demyelinating disease." (PMID 40722873, 2025). "In clinical trials involving patients with rheumatoid arthritis, tocilizumab, the only anti-IL-6R mAb currently under investigation for BD (including a few cases of GIBD), appeared to pose a risk of serious and opportunistic infections, similar to anti-TNF-α agents in clinical use." (PMID 39857830, 2025). "Etanercept was the first TNF α inhibitor, approved on August 24, 1998, for treating rheumatoid arthritis (RA)." (PMID 40525119, 2025). "Atypical CD62L- naïve CD4 T cells have been described in rheumatoid arthritis (RA), where they correlate with disease flares and exhibit IL-1/IL-6/TNF-driven inflammatory signatures." (PMID 40661940, 2025). "The TNF-positive EVs derived from FLSs in rheumatoid arthritis (RA) have been confirmed to induce apoptosis resistance in T cells." (PMID 40176023, 2025). "Tumor necrosis factor-α (TNF-α) inhibitors have greatly enhanced the management of inflammatory diseases such as rheumatoid arthritis (RA) and inflammatory bowel disease." (PMID 41523451, 2025). "However, the abnormal secretion of TNF-α is harmful and may lead to rheumatoid arthritis, inflammatory bowel disease, psoriatic arthritis, ankylosing spondylitis, psoriasis, and noncommunicable uveitis." (PMID 40430440, 2025). "Treatments for conditions like rheumatoid arthritis (RA) include anti-TNF agents, anti-IL-6 receptor antagonists, anti-CD20 antibodies, and T-cell co-stimulation inhibitors." (PMID 40082977, 2025).
rheumatoid arthritis (continued). "Furthermore, studies from a large randomized cardiovascular safety trial and an extended analysis of phase 3b/4 safety data demonstrated a higher incidence of major adverse cardiovascular events and cancer in patients with rheumatoid arthritis receiving tofacitinib compared to anti-TNF." (PMID 40283992, 2025). "In rheumatoid arthritis (RA), levels of PC increase in response to inflammatory mediators such as TNF-α, PDGF, and IL-1β." (PMID 40821837, 2025). "Importantly, the NF-κB signaling pathway, TNF signaling pathway, rheumatoid arthritis, IL-17 signaling pathway, osteoclast differentiation, cytokine-cytokine receptor interaction, and chemokine signaling pathway were highly activated in periarticular CD14hi macrophages of Spry1-cKO mice." (PMID 40471688, 2025). "This study aims to investigate the impact of the pro-osteoblastogenic ERK-activated ribosomal S6 kinase (Rsk2) on Tumor necrosis factor (TNF)α-induced bone loss in the craniofacial system, focusing on its role in rheumatoid arthritis (RA)." (PMID 40140815, 2025). "Our recent report indicated that the clinicopathological features of rheumatoid arthritis-associated lymphoproliferative disorder (RA-LPD) also vary based on the other anti-RA agents used, such as tacrolimus and tumor necrosis factor inhibitors." (PMID 40725854, 2025). "This involves overactivation of inflammatory pathways [e.g., IFN-α in lupus, TNF-α in rheumatoid arthritis (RA)] and dysregulated B/T cell responses, leading to chronic inflammation and progressive tissue damage." (PMID 40843358, 2025). "Similarly, anti-TNFα therapy has been shown to reverse compromised Treg function in rheumatoid arthritis, and tyrosine kinase 2 (TYK2) inhibitors might prove superior to Janus kinase 1 (JAK1) inhibitors in the treatment of PsoA regarding Treg function." (PMID 40806470, 2025). "TNF-α levels increase both locally and systemically in chronic inflammatory diseases such as psoriasis, rheumatoid arthritis (RA), ankylosing spondylitis (AS), and Crohn’s disease." (PMID 40711067, 2025). "Tumor necrosis factor (TNF) inhibitors have significantly improved outcomes for patients with rheumatoid arthritis (RA)." (PMID 41158918, 2025). "One example is that TNF is important in the pathogenesis of rheumatoid arthritis (RA) and a confirmed drug target for RA." (PMID 40299348, 2025). "In rheumatoid arthritis a randomized trial reported a 4-year major adverse cardiovascular events (MACE) of 3.4% with tofacitinib 5 mg BID and 4.2% with 10 mg BID, compared with 2.5% with anti-TNF therapy, with higher risk in patients ≥ 65 years or with prior atherosclerotic cardiovascular disease." (PMID 41301759, 2025). "Although TNF-α has a key role in the normal course of the immune response, its overproduction leads to a damaging effect and is important for the pathogenesis of a number of autoimmune diseases, such as rheumatoid arthritis, inflammatory bowel diseases, and psoriasis, among others." (PMID 39683190, 2024). "These gene-enriched pathways, including the rheumatoid arthritis pathway, NF-κB pathway, TNF pathway, and osteoclast differentiation pathway, are well documented in the pathogenesis of RA." (PMID 38166916, 2024). "The discovery of tumor necrosis factor (TNF-α) as a crucial cytokine in the pathogenesis of ARDs as rheumatoid arthritis (RA) led to the development of the first group of biologic drugs: TNF-α inhibitor." (PMID 39742256, 2024). "Anti-TNF monoclonal antibodies have been used for the treatment of rheumatoid arthritis (RA) and inflammatory bowel disease, and anti-IL-17 antibodies have also shown some efficacy for the treatment of RA." (PMID 39544925, 2024). "Tumor necrosis factor inhibitors (TNFis) are commonly utilized in treating rheumatoid arthritis (RA), yet their response rate can be as low as 70%." (PMID 39502698, 2024).